KMT2A (lysine methyltransferase 2A)
Diseases named in the same sentence as KMT2A in open-access papers (continued):
Sharing a sentence is not in itself a finding about the gene and the disease.
leukemia (continued). "We identified SID7969543, an inhibitor of transcription factor Nuclear Receptor Subfamily 5 Group A Member 1 (NR5A1), as a novel selective candidate inhibitor against a subset of KMT2A-r and CALM-AF10 translocated leukemia cells, including cells derived from infants with KMT2A-r leukemia." (PMID 35127484, 2021). "Furthermore, approximately 80% of infant ALL cases carry leukemia-specific chromosomal translocations of the Mixed Lineage Leukemia (MLL, or KMT2A) gene, and this patient group in particular fares significantly worse with EFS rates of 30–40%." (PMID 34201500, 2021). "In KMT2A-rearranged leukemias, the transcriptional consequences of Men1 deletion/Menin/KMT2A inhibition mirror inactivation of the fusion, not inactivation of the KMT2A wild type allele." (PMID 33542482, 2021). "Both 1° AML-3 and 1° MPAL-1 carry a KMT2A–AF9 fusion protein, whereas KOPN-8 carries a KMT2A–ENL fusion, suggesting that the AF9 fusion partner recruits particularly high levels of DOT1L to oncoprotein target loci while other leukemias can be variable for DOT1L recruitment." (PMID 34663924, 2021). "Leukemias driven by rearrangements of the lysine methyltransferase 2A (KMT2A, previously known as MLL) gene do not respond well to treatment and have a very poor prognosis." (PMID 34088716, 2021). "Several novel agents such as DOT1L and FLT3 inhibitors that demonstrated selective targeting of KMT2A-r leukemia cells in preclinical models, have unfortunately failed to live up to their expectations in clinical trials." (PMID 35127484, 2021). "Furthermore, KMT2A (also known as MLL) is a known oncogenic driver in translocations with other partner genes in sarcomas and leukemias." (PMID 33674910, 2021). "This could indicate that discrepancies in the regulation of KMT2A and KMT2D in engrafted leukemia also affect specific target genes." (PMID 33722259, 2021). "MN1-driven leukemia is characterized by a CMP-like gene expression program that includes high expression of Hoxa9 and Meis1, known target genes of Kmt2a-fusion proteins but also of wild type Kmt2a." (PMID 33542482, 2021). "In addition, KMT2A rearrangements are also prevalent in mixed-phenotype acute leukemia (MPAL), and numerous examples of KMT2Ar leukemias that interconvert between lineage types have been documented." (PMID 34663924, 2021). "The loss of PHD fingers in KMT2A due to genomic translocation in MLL-r leukemia is responsible for the transforming potential of the resulting fusion proteins, which indicates the role of PHD fingers in the correct recruitment of KMT2A into the genomic loci." (PMID 33302406, 2020). "The function of the chimeric proteins in KMT2A-rearranged leukemia is not entirely understood, but KMT2A fusion proteins have been shown to interfere with transcriptional elongation and thereby deregulate expression of target genes." (PMID 32727569, 2020). "Notably, we report amplification of the corresponding syntenic region (11q23) in a subset of human leukemia leading to the overexpression of several cancer genes, including MLL/KMT2A." (PMID 31167132, 2019). "Chromosomal translocations of 11q23 of the mixed lineage leukemia gene (known as KMT2A, MLL, or HRX) account for 5–10% of all acute leukemia cases, including acute lymphoid, myeloid, and biphenotypic leukemia, and are generally associated with inferior prognosis." (PMID 30003105, 2018). "In hematopoietic cells, KMT2A translocations result in oncogenic fusion proteins that recruit DOT1-like histone H3K79 methyltransferase, which changes the epigenetic identity of the cells and drives a subset of infantile and adult leukemias." (PMID 28968975, 2017). "Despite the observation that KMT2A genomic alterations (except KMT2A‐rearrangements in leukemia) seem to have no overall impact on the prognosis of cancer patients, the integrity and function of the KMT2A/Menin complex seems to be important in a variety of cancer types." (PMID 39887730, 2026).
leukemia (continued). "It is typically necessary to prove the diagnosis of secondary tumors, rather than a lineage switch at relapse, for types of leukemia that demonstrate increased lineage plasticity, such as AL with KMT2A, ZNF384 or DUX4 gene rearrangements or early T-cell acute lymphoblastic leukemia (ETP-ALL)." (PMID 40565358, 2025). "Although a recent study revealed that the immunoproteasome subunit PSMB8 maintains oncogenic gene expression in KMT2A complex-driven leukemia, we first found that the increased PSMB10 but not PSMB8 is involved in chemotherapeutic drug-resistant LSC maintenance via senescent and immune regulation." (PMID 40462177, 2025). "However, regardless of fusion partners, KMT2A-rearranged leukemias typically exhibit poor prognoses, characterized by progression-free survival (PFS) rates of 30–40% and overall survival (OS) rates < 25%." (PMID 40361241, 2025). "Interestingly, KMT2A-rearranged AML has high MEF2D expression, which might play a critical role in leukemia development." (PMID 38473221, 2024). "Notably, although the leukemia cells no longer express certain KMT2A-regulated genes, they still rely on the KMT2A-fusion protein for survival." (PMID 39682203, 2024). "Indeed, studies analysing drug responsiveness in ZNF384- and MLL/KMT2A-childhood ALL, suggested that FLT3 targeting therapy could be considered in these forms of leukaemia, especially in ZNF384-ALL." (PMID 38049555, 2024). "Interestingly, in the literature SMAD1 has not yet been mentioned in the context of KMT2A-rearranged leukemia." (PMID 39834944, 2024). "However, KMT2A alterations in leukemia, particularly mixed lineage leukemia, are not small local changes, but chromosomal translocations generating novel fusion proteins." (PMID 36598580, 2023). "Thus, we conclude that the biology of PHDs is relevant for KMT2A-D loss-of-function malignancies, but not for translocation-driven KMT2A gain-of-function leukemia." (PMID 36598580, 2023). "In this approach both copies of the wild-type KMT2A gene are present which is not found in KMT2Ar leukemias resulting in unknown regulatory effects by the wild-type protein." (PMID 35756660, 2022). "Additional KMT2A/MLL-R+ patients whose leukemia cells do not have amplified FLT3 gene expression but an activating FLT3 mutation like FLT3-ITD may also benefit from the use of FLT3 inhibitors." (PMID 36627892, 2022). "Thus, Menin/KMT2A inhibition in KMT2A-fusion leukemias acts via disruption of the fusion complex, not the KMT2A complex." (PMID 33542482, 2021). "In addition, KMT2D can interact with KMT2A in acute myeloid leukemia, its deletion reduced MLL-AF9 leukemia cell survival, and the codeletion of both KMT2A and KMT2D resulted in more severe reductions in survival, proliferation, and gene expression than either individual gene deletion." (PMID 32164600, 2020). "A recent preclinical study indicated that Pinometostat enhances the sensitivity of pediatric AML cells to Sorafenib, a multi-kinase inhibitor, regardless of KMT2A-r status, suggesting that combination therapy with Pinometostat may still hold value in pediatric leukemia." (PMID 40361241, 2025). "Besides its role in facilitating H3K4 methylation through the KMT2A complex, DPY30 itself regulates the differentiation and proliferation of haematopoietic stem cells and progenitor cells, and it promotes cell growth in leukaemia cells induced by KMT2A fusion genes." (PMID 39888275, 2025). "Additionally, our results hint at a previously unknown role and dependency of some non-MLLr leukemias on KMT2A expression." (PMID 38003662, 2023).
leukemia (continued). "Given that kinases represent the largest group of druggable targets in the human genome, and that KMT2A-r ALL is an epigenetically driven malignancy, combinations of epigenetic-based drugs and kinase inhibitors may well represent effective treatments for this elusive type of leukemia." (PMID 37686014, 2023). "With the important caveat that this case will not represent all KMT2A-rearranged B-ALL, it demonstrates that the cell of origin cannot be inferred from the transcriptional phenotype of leukemia cells." (PMID 35288693, 2022). "While HOXA gene upregulation is a common feature, rare KMT2A rearrangements may occur without pronounced HOXA dysregulation, highlighting a degree of heterogeneity among these leukemias." (PMID 40374809, 2025). "Converse to KMT2A-rearranged AML, KMT2A-PTD enhances self-renewal of hematopoietic stem cells by blocking the cell differentiation but is not sufficient by itself to induce overt leukemia." (PMID 34068470, 2021). "Thus, the SET domain of Kmt2a (and therefore the corresponding histone methyltransferase activity) is not required for the establishment of MN1-driven leukemia in vitro or in vivo." (PMID 33542482, 2021). "Therefore, our results should not be interpreted to suggest that FLT3 inhibitors would be preferentially active in pediatric AML patients with KMT2A/MLL rearrangements, as many cases without KMT2A/MLL rearrangements whose leukemia cells are FLT3-ITD+ may also benefit from FLT3 inhibitors." (PMID 36627892, 2022).
acute myeloid leukemia (285 papers, 2006 to 2026). Acute myeloid leukemia (AML) is a group of neoplasms arising from precursor cells committed to the myeloid cell-line differentiation. "With the known promiscuity associated with the KMT2A gene, shown to partner with greater than 80 other genes, rearrangements involving this gene are well documented in acute lymphoblastic and acute myeloid leukemias." (PMID 40725454, 2025). "KMT2A PTDs, most frequently found in exons 2 to 9, occur in approximately 10% of myelodysplastic syndrome/acute myeloid leukemia (MDS/AML) cases and are linked to disease progression and relapse." (PMID 40361241, 2025). "Enrichment of rare heterozygous frameshift variants in KMT2A and C has been reported in acute myeloid leukemia (AML), IL, and solid tumors." (PMID 36479909, 2023). "KMT2A rearrangements (KMT2A-r) are among the most common structural aberrations in pediatric acute myeloid leukemia (AML) and are very important for the risk group stratification of patients." (PMID 34638301, 2021). "Overall, KMT2A plays a key role in embryonic development, neurodevelopment, and hematopoiesis, while altered KMT2A expression is associated with multiple pathologic conditions, especially blood cancers such as acute myeloid leukemia." (PMID 39972178, 2025). "For instance, the partial tandem duplication of the KMT2A gene is linked to upregulated KMT2A expression in acute myeloid leukemia (AML), contributing to AML development by promoting uncontrolled cell proliferation and inhibiting normal cellular differentiation." (PMID 39369032, 2024). "KMT2A translocations can cause different forms of hematological malignancies including acute myeloid leukemia, different types of acute lymphocytic leukemia, myelodysplastic syndrome, and lymphoblastic lymphoma and therefore affect more than one specific cell type." (PMID 38201282, 2023). "The project GENIE, led by the American Association for Cancer Research, highlighted how KMT2A is implicated in many diseases, especially in blood cancers such as acute myeloid leukemia (2.49%), T-cell lymphoblastic leukemia (5.63%) and up to 14% in high grade B-cell lymphoma." (PMID 35328068, 2022). "KMT2A-rearranged (KMT2A-r) acute myeloid leukemia (AML) is an aggressive AML subtype characterized by 11q23 chromosomal rearrangements involving KMT2A gene and clinically associated with poor prognosis." (PMID 42014858, 2026). "Among 113 CMML patients, 23(20.4%)were re-diagnosed as acute myeloid leukemia(AML), including 18 AML with NPM1 mutation, 3 AML with KMT2A rearrangement, and 2 AML with MECOM rearrangement." (PMID 37550186, 2023). "Acute myeloid leukemia (AML) with partial tandem duplication of histone-lysine N-methyltransferase 2A (KMT2A-PTD) is a subtype of AML and is associated with adverse survival, yet the molecular pathogenesis of KMT2A-PTD is not fully understood." (PMID 32015320, 2020). "KMT2A-rearranged acute myeloid leukemia is driven by epigenetic dependencies yet remains clinically resistant to therapies targeting individual regulators, indicating that resistance reflects compensatory regulation across an epigenetic network." (PMID 41882099, 2026). "Menin (MEN1) is a well-recognized powerful tumor promoter in acute leukemias (AL) with KMT2A rearrangements (KMT2Ar, also known as MLL) and mutant nucleophosmin 1 (NPM1m) acute myeloid leukemia (AML)." (PMID 39796769, 2025). "Chromosomal rearrangements involving KMT2A (KMT2A-r) occur in 20% of paediatric acute myeloid leukaemia (AML)." (PMID 40965326, 2025). "KMT2A‐r‐AML is a subtype of acute myeloid leukemia that primarily affects cells of the myeloid lineage, which causes the bone marrow to produce an excessive amount of immature myeloid cells." (PMID 39428967, 2024).
acute myeloid leukemia (continued). "Menin is also critical in regulating genes that drive cancer growth in acute myeloid leukemia (AML), and more recently, targeting menin’s interaction with KMT2A has emerged as a promising therapeutic strategy for treating AML, especially with KMT2A rearrangement and NPM1 mutations." (PMID 39594699, 2024). "Lysine methyltransferase 2A (KMT2A) rearrangements are commonly found in juvenile acute myeloid leukaemia (AML)." (PMID 39280986, 2024). "KMT2A-rearrangede acute myeloid leukemia (KMT2A-r AML) is an acute leukemia characterized by a chromosomal translocation of the KMT2A gene, and it has poor outcomes." (PMID 39830983, 2024). "KMT2A‐r‐AML specifically manifests as an acute myeloid leukemia subtype, often exhibits a complex genetic landscape, and the specific KMT2A fusion partner genes can vary, contributing to the heterogeneity of the disease." (PMID 39428967, 2024). "KMT2A partial tandem duplications (PTD), most commonly involving exons 2 to 9, are observed in 10% of myelodysplastic syndrome/acute myeloid leukemia (MDS/AML) cases, and are associated with disease progression and relapse." (PMID 39303915, 2024). "Translocations involving the KMT2A gene occur in nearly 10% of acute leukemias and are observed in both acute myeloid leukemia (AML) and acute lymphoblastic leukemia (ALL)." (PMID 38030791, 2024). "The interaction of menin with KMT2A protein is considered responsible for the leukemogenesis in acute myeloid leukemia (AML) through the upregulation of the HOX/MEIS1 genes." (PMID 39594904, 2024). "Lysine methyltransferase 2A-rearranged acute myeloid leukemia (KMT2A-r AML) is a special entity in the 2022 World Health Organization classification of myeloid neoplasms, characterized by high relapse rate and adverse outcomes." (PMID 38026790, 2023). "In 2002, a genetic alteration in the TET1 gene was identified through the detection of a chromosomal rearrangement, specifically the translocation 10q22-11q23 of TET1 and Lysine Methyltransferase 2A (MLL1) genes in acute myeloid leukemias." (PMID 38203443, 2023). "Acute myeloid leukemia with KMT2A (MLL) rearrangements is characterized by specific patterns of gene expression and enhancer architecture, implying unique core transcriptional regulatory circuitry." (PMID 35301220, 2022). "Acute leukemias in which the mixed lineage leukemia (MLL, also called MLL1 or KMT2A) gene is translocated at 11q23 accounts for approximately 35–50% of pediatric acute myeloid leukemia (AML) and up to 80% of acute lymphocytic leukemia (ALL)." (PMID 35331314, 2022). "A key feature of such therapy-induced acute myeloid leukemia (t-AML) is recurrent chromosomal translocations involving AML1 (RUNX1) or MLL (KMT2A) genes." (PMID 36077220, 2022). "KMT2A alterations have been reported in several blood cancers such as mixed-lineage, acute lymphoblastic and acute myeloid leukemia." (PMID 35328068, 2022). "A specific alteration called KMT2A-PTD has been previously found in 5% of newly diagnosed acute myeloid leukemia cases." (PMID 34068470, 2021). "Recently, a new subset of acute myeloid leukemia (AML) presenting a direct partial tandem duplication (PTD) of the KMT2A gene was described." (PMID 34068470, 2021). "Acute myeloid leukemia (AML) with rearrangement of the lysine methyltransferase 2a gene (KMT2Ar) has adverse outcomes." (PMID 34588432, 2021). "USP2 is identified as a fusion partner of MLL (also known as KMT2A) in infant acute myeloid leukemia by using a whole transcriptome sequencing analysis." (PMID 34454635, 2021). "PML-RARA, RUNX1-RUNX1T1, and KMT2A-rearrangement are common genetic rearrangements that drive the development of acute myeloid leukemia (AML)." (PMID 29688850, 2018). "Additionally, in some subtypes of acute myeloid leukemia, genomic rearrangements involving the lysine methyltransferase 2A gene KMT2A yield fusion proteins that drive oncogenesis." (PMID 40698074, 2025).